NLRP3 (NLR family pyrin domain containing 3)
Diseases named in the same sentence as NLRP3 in open-access papers (continued):
Sharing a sentence is not in itself a finding about the gene and the disease.
lung carcinoma (continued). "Simvastatin, a classical anti-hyperlipidemic drug, was reported to induce pyroptosis by activating the NLRP3 inflammasomes caspase-1-IL-18 and IL-1β axes in H1299 and A549 lung cancer cell lines without causing poisonousness tohealthy lung cells." (PMID 38016064, 2023). "Previous studies have revealed that NETs could promote NSCLC metastasis through the NF-κB/NLRP3 inflammatory pathway and facilitate metastasis of circulating lung carcinoma cells to the liver after surgery." (PMID 36910600, 2023). "In this study, A 549 lung cancer cells were induced with inflammation through the NLRP3 inflammasome pathways using LPS bacterial inflammation-inducing agents in combination with adenosine triphosphate (ATP), and measured cell proliferation using colony formation assay." (PMID 38026959, 2023). "Therefore, NLRP3 inflammasome has a complex and dual role in lung cancer erythematosus, depending on the context and stage of the disease." (PMID 37715239, 2023). "Our results suggest that NR1D1 acts as a tumor suppressor in lung cancer development, indicating that NLRP3 inflammasome blockade via NR1D1 activation could be a therapeutic option for lung cancer patients." (PMID 37524704, 2023). "Besides, the levels of NLRP3, cleaved caspase-1, IL-1β and IL-18 were increased in the two lung cancer cells." (PMID 36276078, 2022). "Moreover, the previous research shows that NLRP3 inflammasome and its products are up-regulated in lung cancer tissues." (PMID 35292015, 2022). "However, which miRNAs affect the migration and invasion of lung cancer cells through regulating NLRP3 remains poorly defined." (PMID 36276078, 2022). "Moreover, in lung cancer, previous studies have shown that NLRP3 can enhance the proliferation of A549 cells through IL-1β/ERK/CREB and IL-18/AKT/CREK signaling pathways, and promote tumor metastasis by reducing E-cadherin and increasing Snail expression." (PMID 36349316, 2022). "Similarly, activation of the NLRP3 inflammasome accelerates tumor proliferation and migration in lung cancer." (PMID 36457716, 2022). "In addition, the levels of NLRP3, cleaved caspase-1, IL-1β and IL-18 were increased in the two lung cancer cells with miR-223-3p inhibition, and the corresponding results were contrary in miR-223-3p mimic group." (PMID 36276078, 2022). "Our previous study showed that NLRP3 inflammasome participated in the tumorigenesis of lung cancer and deletion of NLRP3 gene could inhibit the occurrence of lung tumors in mice induced by B(a)P or B(a)P combined with LPS." (PMID 36276078, 2022). "Then, the migration and invasion of lung cancer cells were detected with miR-223-3p mimic and inhibitor using Transwell assay, at the same time the expression of NLRP3, cleaved caspase-1, IL-1β and IL-18 was determined using Western Blot and immunohistochemistry assay." (PMID 36276078, 2022). "Exosomes derived from lung cancer cells secrete TRIM59 and transform macrophages into tumor-promoting macrophages by regulating ABHD5 proteasome degradation, which activates the NLRP3 inflammasome signaling pathway and promotes the progression of lung cancer by secreting IL-1." (PMID 34511114, 2021). "Taking into account all these data, it is therefore proposed that blocking of NLRP3 inflammasome activation may serve as a therapeutic target for preventing lung cancer progression." (PMID 34094030, 2021). "In terms of tumors, the NLRP3 inflammasome could enhance the proliferation and migration of A549 lung cancer cells, and an increased expression of NLRP3 was positively correlated to tumor growth in oral squamous cell carcinoma (OSCC)." (PMID 34298833, 2021). "Huaier Extract could inhibit Cell proliferation and in-vivo tumor growth in lung cancer through activating NLRP3-dependent pyroptosis." (PMID 33456359, 2021).
lung carcinoma (continued). "Since it has previously been reported that upon activation, NLRP3 inflammasome induces proteolytic cleavage and conversion of pro-IL-1β to IL-1β and IL-1β, in turn, promotes proliferation and migration of the lung cancer cells as well as tumor growth and angiogenesis." (PMID 34094030, 2021). "Therefore, in this study we selected a prostate cancer cell line, PC3, and lung cancer-derived cell line, A549, to investigate the impact of doxycycline on NLRP3 activation." (PMID 34577552, 2021). "Collectively, these data indicate that tumor-derived exosomal TRIM59 converts macrophages to tumor-promoting functions of macrophages via regulating ABHD5 proteasomal degradation, to activate NLRP3 inflammasome signaling pathway to promote lung cancer progression by IL-1β secretion." (PMID 32867817, 2020). "In sum, our results showed that, tumor-derived exosomal TRIM59 converts macrophages to tumor-promoting functions of macrophages via regulating ABHD5 proteasomal degradation, to activate NLRP3 inflammasome signaling pathway to promote lung cancer progression by IL-1β secretion." (PMID 32867817, 2020). "Although MCC950, a potent small molecule inhibitor of NLRP3 inflammasome, was previously reported to inhibit survival, migration, and invasion in head, neck, and lung cancer, the effect of caspase-1 inhibitors, such as Ac-YVAD-cmk, on tumor growth remains controversial." (PMID 32155890, 2020). "Consistently, reduced NLRP3-dependent IL-1β secretion is observed in AMs isolated from the bronchoalveolar lavage of lung cancer patients despite a systemic higher NLRP3 inflammasome activation and IL-1β secretion in peripheral blood leukocytes from these patients." (PMID 30832375, 2019). "However, the mechanism of NLRP3 expression and NLRP3 inflammasome activation in inflammation-related lung cancer should further investigate." (PMID 30696442, 2019). "Nanoparticles (NP) such as silica and asbestos may result in the overexpression of NLRP3 inflammasomes, and the secretion of caspase-1 and IL1β in the in vivo model of lung cancer." (PMID 30447690, 2018). "The NLRP3 inflammasome expression and role in lung cancer is relatively unknown, while inflammatory reactions can exert a dual influence on tumor growth and progression." (PMID 30365491, 2018). "Given the ability of NLRP3 in promoting immunogenic cell death, the activation/ reprogramming of dysfunctional AMs, could be a novel add-on therapy in established lung cancer." (PMID 30365491, 2018). "Further, inhibition of enhanced NLRP3 inflammasome by EP might be a new therapeutic candidate for treating inflammation-promoted cell growth and migration of human lung cancer cells." (PMID 30560887, 2018). "In addition, in a subcutaneous tumor model of lung cancer in mice, we observed that NLRP3 inflammasome and downstream IL-1β could promote tumor angiogenesis and lymphangiogenesis, as well as tumor growth." (PMID 39230586, 2024). "However, several studies have supported the role of NLRP3 in lung cancer." (PMID 39769450, 2024). "NR1D1-deficient mice showed increased NACHT, LRR, and PYD domain-containing protein 3 (NLRP3) inflammasome activation, and conditioned medium (CM) from NR1D1-deficient macrophages increased the proliferation and epithelial–mesenchymal transition (EMT) of lung cancer cells." (PMID 37524704, 2023). "Therefore, a triple therapy of XRT + NLRP3 agonist + α-PD1 might be an alternative therapeutic approach for patients with immune-resistant lung cancer." (PMID 37289257, 2023). "Furthermore, we examined whether IL1β and IL18, which are the downstream mediators of the NLRP3 inflammasome, can promote the proliferation of lung cancer cells." (PMID 37524704, 2023). "A role of NLRP3 inflammasome-driven inflammation in cancer development was partly supported by the finding that the anti-IL-1β therapy using canakinumab in the CANTOS trial is correlated with a reduction in the incidence of lung cancer in the patient population studied." (PMID 36669831, 2023).
lung carcinoma (continued). "Thus, suppression of the NLRP3 inflammasome might also be an effective strategy in the treatment of lung cancer." (PMID 36364001, 2022). "However, which miRNAs affect the migration and invasion of lung cancer cells through regulating NLRP3 still remain unknown." (PMID 36276078, 2022). "Besides, it was found that NLRP3 inflammasome activation could promote nicotine-induced lung cancer cell proliferation and migration." (PMID 36276078, 2022). "NLRP3 inflammasome activation-induced IL-1β and IL-18 in lung cancer may work through mechanisms other than the caspase-1 pathway, indicating that NLRP3 inflammasome can mediate the release of IL-1β and IL-18 through caspase-1-dependent or -independent pathways." (PMID 33613533, 2020). "Similarly, activation of NLRP3 inflammasome in mesothelial cells of lung cancer leads to an inflammatory response that fuels cancer initiation and progression and then activates the NF-κB-signaling pathway in lung cancer, consequently increasing proliferation and inhibiting apoptosis." (PMID 33613533, 2020). "Thus, our results verified that B(a)p or B(a)p plus LPS could induce lung cancer, especially lung adenoma, and successfully provided some evidence regarding the role of NLRP3 in inflammation-driven lung tumorigenesis through our mouse models." (PMID 30696442, 2019). "NLRP3 is known as an intracellular receptor involving inflammation and has been reported which is increasingly associated with tumor development, but the role in inflammation-driven lung cancer has not been fully clarified." (PMID 30696442, 2019). "LINC00969 collaborated with EZH2 to transcriptionally modulate the levels of H3K27me3 in the NLRP3 promoter region, thereby epigenetically suppressing NLRP3 expression, conferring an anti-pyroptotic phenotype, and enhancing TKI resistance in lung cancer." (PMID 40701777, 2025). "These epigenetic modifications suppress NLRP3 expression, inhibit the activation of the NLRP3- caspase-1- GSDMD pathway, and confer an anti-pyroptotic phenotype to lung cancer cells." (PMID 39994107, 2025). "RRx-001 selectively inhibits NLRP3, currently in a Phase III trial for the treatment of lung cancer." (PMID 41280719, 2025). "The activation of NLRP3 inflammasome could promote the proliferation and migration of lung adenocarcinoma A549 cells by mediating the release of IL-18 and IL-1β through the caspase-1 dependent pyroptosis pathway, while blocking IL-18 and IL-1β signaling could inhibit the progression of lung cancer." (PMID 37194012, 2023). "It is reported that increased NLRP3 inflammasome, AIM2 inflammasome, caspase-1, IL-1β, and IL-18 are found in lung cancer cells." (PMID 35819638, 2022). "Ginkgolide B induced autophagy in lung cancer cells and inhibited the NLR family pyrin domain containing 3 (NLRP3) inflammasome in one study." (PMID 35630688, 2022). "NLRP3 was activated in a prostate cancer cell line (PC3) and a lung cancer cell line (A549) before treatment with doxycycline." (PMID 34577552, 2021). "As caspase-1 was the major downstream molecule of NLRP3 inflammasome, its inhibitor Z-YVAD-FMK attenuated LPS+ATP-induced A549 lung cancer cells proliferation." (PMID 34211462, 2021). "In this study, we found that human lung cancer cell-released MPs trigger the TLR3 and NLRP3 inflammasome pathways in macrophages, leading to the secretion of IL-1β." (PMID 31649305, 2020). "NLRP3 inflammasome components NLRP3, ASC, and Caspase-1 were found to be highly expressed in lung cancer cell lines and tissues than in adjacent normal tissues." (PMID 28865486, 2017). "In parallel, two human lung cell lines—L132 (normal bronchial epithelial cells) and A549 (lung carcinoma cells)—were irradiated with 6 Gy X-rays and treated with CYNC-2 to assess cell viability and changes in AMPK/NLRP3 pathway markers via qPCR and immunofluorescence." (PMID 41303320, 2025).
lung carcinoma (continued). "To evaluate the clinical relevance of NLRP3 inflammasome activation in radiation-induced lung injury (RILI), we analyzed lung specimens obtained from four patients with locally advanced lung cancer who had undergone neoadjuvant concurrent chemoradiotherapy (CCRT) followed by surgery." (PMID 41303320, 2025). "The significance of NLRP3 in lung cancer is further confirmed by a mouse study where NLRP3-null mice inhibit lung cancer growth induced by benzo(a)pyrene without or with lipopolysaccharide (LPS) cotreatment." (PMID 39769450, 2024). "Surprisingly, the inflammatory response involving NLRP3 was only activated in lung epithelial cells but not in lung cancer cells after radiation." (PMID 36694200, 2023). "To examine whether NLRP3 inflammasome activation is involved in increased lung tumor development in Nr1d1−/− mice, we treated mice with MCC950, a specific inhibitor of the NLRP3 inflammasome, in orthotopic LLC1 lung cancer models." (PMID 37524704, 2023). "In addition, NLRP3 plays an important role in many kinds of cancers, such as CRC, HCC, GC, head and neck cancer, oral cancer, lung cancer, and so on." (PMID 37415625, 2023). "In conclusion, we found that IL-17A promotes the migration, invasion and the EMT process of lung cancer cells in vitro without affecting cell proliferation, and this process was accompanied by NLRP3 activation." (PMID 36349316, 2022). "TRIM59 directly induces the ubiquitination of ABHD5, leading to its proteasome-dependent degradation, activating the NLRP3 inflammasome signaling pathway, and promoting the secretion of IL-1β by macrophages; As the final result, exosomal TRIM59 facilitates lung cancer growth and metastasis." (PMID 35047512, 2021). "Our results showed that NR1D1 in the tumor microenvironment functions as a tumor suppressor by negatively regulating the NLRP3 inflammasome, suggesting that the NLRP3 inflammasome blockade via NR1D1 activation could be a therapeutic strategy to overcome lung cancer." (PMID 37524704, 2023). "However, to date, there has been no relevant research on the role of NLRP3 in lung cancer cells stimulated by IL-17A." (PMID 36349316, 2022). "However, at present, it has only been reported that chemotherapeutic drugs induced cell pyroptosis in lung cancer by the NF-κB pathway, ROS inducing, APE1 target as well as NLRP3 inflammasome, and much remains unknown about the regulatory mechanisms." (PMID 36039017, 2022). "The overexpressed NLRP3 could mimic silica-induced DNA damage and mutagenic double-strand breaks that were documented as increased levels of γ-H2AX, p-CHK2 in airway epithelial cells and closely related to the occurrence of lung carcinomas." (PMID 34660289, 2021).
liver diseases (115 papers, 2015 to 2026). "NOD-like receptor thermal protein domain associated protein 3 (NLRP3) activation is involved in various liver diseases." (PMID 40799819, 2025). "Portal hypertension (PHT)‐induced mouse models in METTL3 mutant or NLRP3‐deficient littermates were established, and nude mouse gastric graft tumour models with relevant inhibitors were generated." (PMID 38616702, 2024). "NLR family pyrin domain containing 3 is a protein complex that plays critical roles in the progression of steatotic liver disease and inflammatory response associated with NAFLD." (PMID 38673787, 2024). "This study highlights potential therapeutic targets in gut dysbiosis and NLRP3 inflammasome activation for mitigating toxin-associated inflammatory liver diseases." (PMID 38093299, 2023). "NLRP3 was reported to play essential roles in the pathogenesis of alcohol-associated liver disease, non-alcoholic fatty liver disease/non-alcoholic steatohepatitis, cirrhosis and fibrosis, which ultimately leads to hepatocellular carcinoma (HCC)." (PMID 36619871, 2022). "Increasing studies have indicated that the aberration of the NLRP3 inflammasome is implicated in liver diseases, including drug-induced liver injury (DILI), hepatocellular carcinoma (HCC), cholestatic liver injury (CLI), and autoimmune hepatitis (AIH)." (PMID 36160411, 2022). "In the context of liver disease, the NLRP3 inflammasome has been implicated in many studies as the primary activator of inflammation and initiates the development of NASH in both rodent models and humans." (PMID 35323681, 2022). "Previous reports suggest that NLRP3 inflammasome-associated pro-inflammatory factor levels increase in several inflammatory liver diseases." (PMID 32347316, 2020). "In this review, we will summarize the current knowledge about the inflammatory function of the NLRP3 inflammasome in sterile inflammation-associated liver disease." (PMID 30213101, 2018). "The activation of the NLRP3 inflammasome and the release of downstream IL-1β and IL-18 have been shown to be associated with the pathogenesis of various liver diseases." (PMID 30105078, 2018). "It appears that both the NLRP3 inflammasome and the IL-33 pathway can become activated in sterile inflammation-associated liver diseases." (PMID 30213101, 2018). "There is compelling evidence that activation of the NLRP3 inflammasome leads to progression of sterile inflammation-associated liver diseases and therefore, components of this inflammatory pathway represent promising new therapeutic targets." (PMID 30213101, 2018). "This study identifies P2X7R and NLRP3 as novel therapeutic targets for liver disease associated with metabolic disorders." (PMID 29270247, 2017). "As the major cause of inflammatory cytokine storm, the NLRP3 inflammasome exacerbates liver diseases, even though it might exert protective effects in regards to hepatitis C and B virus infection (HCV and HBV)." (PMID 38674122, 2024). "Thus, providing a basis for the therapeutic potential of targeting the NLRP3 inflammasome in the mitigation of toxin associated inflammatory liver diseases." (PMID 38093299, 2023). "The IL-1β /NLRP3 inflammasome cascade may therefore present an attractive target for treating liver disease induced by HCV and other causes of liver inflammation." (PMID 30811485, 2019). "Based on these findings and the fact that both the NLRP3 inflammasome and IL-33 pathway play a role in the pathology of most of the sterile inflammation-associated liver diseases, it would make sense to study a possible NLRP3-IL-33 axis in sterile liver inflammation in more detail." (PMID 30213101, 2018). "However, it remains unclear whether adiponectin can affect NLRP3 inflammasome expression in hepatic diseases and its potential underlying mechanism." (PMID 33251225, 2020).